GPX4 (glutathione peroxidase 4)
Diseases named in the same sentence as GPX4 in open-access papers (continued):
Sharing a sentence is not in itself a finding about the gene and the disease.
tumor (continued). "Additional research is necessary to clarify the function of GPX4 in modulating neutrophils within the TME and its implications for oncogenesis and tumor progression." (PMID 41142608, 2025). "In vivo, sh-RNLS reduced tumor volume/weight, as well as RNLS/STAT3, Ki-67, GPX4, and GSH, while increasing MDA." (PMID 40799250, 2025). "Recent studies found that some red algae-derived terpenoids can inhibit both GPX4 and FSP1, thereby blocking the drug resistance pathway of tumor cells, which provides a direction for the development of multi-target ferroptosis inducers." (PMID 40559667, 2025). "The PtMnIr induce ferroptosis by downregulating GPX4 and promoting LPO, while simultaneously activating the cGAS-STING pathway through Mn2+ release, which sensitizes tumor cells to innate immune responses." (PMID 40846966, 2025). "This dual mechanism triggers a self-reinforcing therapeutic cycle: ferroptosis releases tumor antigens, activating CD8+ T cells to secrete interferon-γ (IFN-γ), which suppresses GPX4 expression and exacerbates LPO, thereby sustaining ferroptotic cell death." (PMID 40846966, 2025). "Tumor tissues from the CIRT group exhibited increased ferroptosis marker ACSL4 and reduced GPX4 expression, consistent with in vitro findings." (PMID 40917841, 2025). "Inhibiting zDHHC8 with the small-molecule compound PF-670462 reduces GPX4 palmitoylation, promotes ferroptosis, and enhances CD8+ T cell infiltration, thereby suppressing tumor growth." (PMID 40919170, 2025). "A central gatekeeper against ferroptosis is glutathione peroxidase 4 (GPX4), an enzyme critical for tumor cell survival that utilizes reduced GSH to detoxify lipid peroxides." (PMID 40535769, 2025). "This strategy enhanced the tumor distribution of RSL3, leading to reduced GSH and GPX4 expression and increased ROS-mediated ferroptosis." (PMID 40328736, 2025). "Inhibited GPX4‐GSH axis and promoted Fe accumulation as well as activated T‐cell immunity in tumor microenvironment." (PMID 40200790, 2025). "It exhibits strong anticancer effects through ferroptosis via IGF2BP3/GPX4 pathways, induces mitochondrial apoptosis, and targets NF-κB, ERK, and PI3K/Akt/mTOR to suppress tumor progression." (PMID 41465430, 2025). "To further evaluate the localization relationship between IDO1 and GPX4, we performed IF staining for IDO1/GPX4 in xenograft mice tumor tissues." (PMID 41438182, 2025). "Conversely, targeting GPX4 or inhibiting it with small molecules like RSL3 induces ferroptosis in cancer cells, effectively overcoming tumor resistance." (PMID 40365295, 2025). "In oral squamous cell carcinoma, HIF-1α can activate GPX4 by inhibiting the transcription of PER1, thus mediating the tumor’s resistance to ferroptosis." (PMID 40709182, 2025). "Ferroptosis is suppressed in GBM by the GPX4–GSH axis, which protects tumor cells from lipid peroxidation." (PMID 40806198, 2025). "In accordance with cell experiment results, lower protein levels of GPX4, p-Stat3, Stat3, SLC7A11 and SLC3A2 were found in nude mice tumor tissues from UA (40 mg/kg) group." (PMID 41341590, 2025). "Sh‐YTHDF2 and DNase I inhibited GPX4, SLC7A11, and FTH1 expression in the tumour, while increasing ACSL4 and PTGS2 levels and had a superimposed effect." (PMID 39865544, 2025). "We also found that macrophage depletion more strongly restored tumor size compared to CD8+ T cell depletion, suggesting that the pivotal role of macrophages in mediating the tumor-suppressive effects of GPX4 knockdown." (PMID 40365295, 2025). "WB and IHC analysis of subcutaneous tumor tissues in the CDX and PDX models showed that TMEM160 knockdown reduced the expression of NRF2 and its target genes, GPX4 and SLC7A11." (PMID 40223081, 2025).
tumor (continued). "Most vitamins and certain bile acids inhibit ferroptosis by upregulating GPX4 or activating antioxidant pathways such as NRF2, thereby potentially enhancing tumor survival." (PMID 41293165, 2025). "Solasodine triggers ferroptosis by upregulating HMOX1 while suppressing GPX4 and SLC40A1, markedly inhibiting tumor growth." (PMID 41373599, 2025). "A pivotal 2014 study established glutathione peroxidase 4 (GPX4) as the central regulator of ferroptosis, with therapeutic implications validated in tumor xenografts." (PMID 40735482, 2025). "This timing dependence is clearly demonstrated by Efimova’s team, who showed that the GPX4 inhibitor RAS-Selective Lethal compound 3 (RSL3) stimulated ICD in tumor cells to activate DCs and induce anti-tumor immunity in an animal tumor model." (PMID 41035634, 2025). "GBM stem-like cells can further drive malignant DC transformation via ZNF148/PTX3 signaling, while tumor-derived exosomes induce ferroptosis in DCs through modulation of the NRF2/glutathione peroxidase-4 (GPX4) pathway, contributing to tumor progression." (PMID 40948940, 2025). "For instance, tumor cells can counteract ICD-triggered LPO via compensatory antioxidant defense mechanisms, such as the GPX4 and ferroptosis suppressor protein 1 (FSP1) pathways." (PMID 41345744, 2025). "Specifically, BP@CPP enhances ROS production, inhibits GPX4 expression, and accelerates GSH depletion in tumor cells via the Cu2+ Fenton reaction." (PMID 40959280, 2025). "We found that peritumoral siRNA‐mediated UBQLN1 knockdown significantly attenuated tumor growth, with western blot confirmation of successful UBQLN1 reduction and concomitant GPX4 downregulation." (PMID 41287824, 2025). "To determine if GPX4 mediates the tumour‐promoting effects of DPP7, we conducted rescue experiments by overexpressing GPX4 in DPP7‐depletion cells." (PMID 40576169, 2025). "For example, in HCC cells and xenograft tumor models in nude mice, curcumin significantly downregulates the expression of SLC7A11, GPX4, GSS, and FTH1, while upregulating ACSL4 and PTGS2, thereby altering the ferroptosis-sensitive phenotype." (PMID 41515171, 2025). "In contrast, SCFAs (such as butyrate) tend to promote ferroptosis and suppress tumor growth by downregulating SLC7A11 and GPX4 expression." (PMID 41293165, 2025). "Our findings demonstrate that targeting GLS1 and GPX4 synergistically inhibits cancer cell growth, suggesting that GLS1 inhibition can sensitise tumour cells to ferroptosis." (PMID 40259435, 2025). "Subsequently, the expression of GPX4 in tumor cells post 131I-Mn/SAE@M treatment was verified at the cellular level, aligning with the in vivo findings, demonstrating a significant reduction in GPX4 expression." (PMID 40968370, 2025). "Tumor molecular markers encompass expression of SLC7A11, GPX4, FSP1, ACSL4, NRF2 pathway activation, and intratumoral labile iron content." (PMID 41301464, 2025). "The photosensitizer Ce6 promotes ferroptosis in tumor cells by generating unilinear oxygen, depleting intracellular glutathione (GSH), and reducing glutathione peroxidase 4 (GPX4)." (PMID 39339402, 2024). "Activation of NFE2L2 in mouse xenograft tumour models also enhanced the expression of FTH1 and GPX4 and decreased the expression of TFRC to some extent." (PMID 38685674, 2024). "Proinflammatory factors can reduce GPX4 levels and trigger ferroptosis in tumor cells, and NLRP3 knockdown in mice can improve the levels of GPX4 in the brain." (PMID 37752806, 2024). "Significant positive correlations with GPX4 (ferroptosis), ACSL4 (fatty acid metabolism), SOD2 (antioxidant), HIF1A (tumor growth and metastasis), FAT1 (fatty acid metabolism) and IREB2 (Iron-responsive element)." (PMID 38206305, 2024).
tumor (continued). "Moreover, the results of immunofluorescence sections of tumors showed that D‐Lycosin‐I could downregulate the expression of GPX4 and upregulate the expression of Cleaved‐Caspase‐3, suggesting that D‐Lycosin‐I could induce ferroptosis and apoptosis of tumor cells in vivo." (PMID 38962935, 2024). "Our study provides insight into the mechanism of anti-tumor activity of CFAs, and in particular, evidence of mitochondrial ROS/lipid ROS as a driver of CMA leading to GPX4 degradation and, ultimately, ferroptosis." (PMID 39643606, 2024). "Studies have demonstrated that the combination of FINs targeting GPX4 and SLC7A11 inhibition with radiotherapy can increase tumor cell ferroptosis, thereby augmenting the tumor-killing effects of radiation." (PMID 39769177, 2024). "Bersuker and colleagues used CRISPR/Cas9 screening methods to screen for apoptosis in cells treated with RSL3 and a tumor single-guide RNA (sgRNA) library and found that FSP1 can inhibit ferroptosis through a GPX4-independent mechanism." (PMID 39664391, 2024). "In MC-38 syngeneic tumor model, (1S, 3R)‐RSL3 (RSL), a glutathione peroxidase 4 inhibitor, effectively promoted the antitumor effect of anti-PD-1 treatment in vivo." (PMID 39128094, 2024). "Specifically, epigenetic mechanisms represented by m6A, NcRNA and some key regulatory proteins, such as GPX4, CD71, ETV4 and SIRT6, interfere with TC progression by regulating tumour cell ferroptosis." (PMID 39163517, 2024). "Tumor cells have the ability to increase the expression of SLC7A11 and GPX4, which helps protect them from ferroptosis induced by radiotherapy." (PMID 38816377, 2024). "Through MHC recognition, CD8+T cells activate the JAK1/STAT1 pathway in tumor cells, impairing the function of System Xc and reducing GSH and GPX4 expression to promote tumor cell ferroptosis." (PMID 38853203, 2024). "CKB phosphorylates GPX4, thereby preventing its degradation and counteracting iron death in HCC cells, ultimately promoting tumor growth." (PMID 38650929, 2024). "OPN promoted tumor sphere formation and angiogenesis in TNBC by activating the PI3K/AKT/mTOR pathway to regulate GPX4-mediated anti-lipid peroxidation levels." (PMID 38526702, 2024). "In an attempt to demonstrate the ferroptosis mechanism of Gi-F-CAA for tumor inhibiting, the GPX4 activity, iron levels, GSH levels, ROS levels, and LPO levels of different treated tumor tissues were estimated, respectively." (PMID 38212623, 2024). "The results suggested that GPX4 inhibitors induced ferroptosis response, ROS elevation, GSH depletion, as well as inhibited tumour cell migration, increased DNA damage and inhibited the mTOR pathway." (PMID 39163517, 2024). "The PIOC@CM NPs encapsulating both Fe3O4 and Ce6 selectively accumulate in the tumor and increase intracellular ROS while decreasing GSH and GPX4 under ultrasonic excitation, ultimately leading to ferroptotic death." (PMID 39309434, 2024). "ART significantly reduced GSH content and GPX4 expression in sunitinib-resistant KTCTL-26 renal cell carcinoma cells to induce ferroptosis, thus exhibiting more potent anti-tumor effects." (PMID 39021832, 2024). "Compared with normal tissues, the relative expression of GPX4, SLC7A11, and Fer1 was significantly upregulated in tumor tissues (p < 0.001)." (PMID 39155888, 2024). "The tumor control group showed a remarkable upregulation for PI3K, p-AKT, and p-mTOR, along with downregulation for the antioxidant SOD and GPX4, as well as decreased levels of GSH and MDA." (PMID 39519654, 2024). "Immunohistochemical staining of the tumor tissues showed elevated levels of 4-HNE in the combination therapy group, whereas expressions of Ki-67 and GPX4 were lower compared to the control group." (PMID 39484165, 2024). "The disulfide bonds play a pivotal role in disrupting intracellular redox homeostasis by depleting glutathione and inactivating glutathione peroxidase 4 (GPX4), synergizing with LND to enhance the sensitivity of tumor cells to ferroptosis." (PMID 38570829, 2024).
tumor (continued). "Recently, several compounds including ML162, RSL3, and DPI were reported to inhibit GPX4 and GSH activity, and promotes MDA activity thereby inducing ROS-mediated ferroptosis induction in tumor cells." (PMID 39097854, 2024). "Meanwhile, overexpression of ferroptosis-inhibiting molecules, such as glutathione peroxidase 4 (GPX4) which is an essential phospholipid peroxidase, can significantly alleviate PCD-mediated necrosis and diminish tumor aggressiveness." (PMID 38890642, 2024). "This is consistent with our findings that silencing CK19 promotes ferroptosis and inhibits tumor growth by activating ACSL4 expression and inhibiting GPX4 expression." (PMID 38987531, 2024). "It was shown that inhibition of ferroptosis by ectopically expressing GPX4 or silencing the expression of ACSL4 can reduce necrosis by 47% or 58–68%, respectively, and prolong the survival of tumor-bearing mice." (PMID 38806658, 2024). "EBV infection-induced GPX4 reduces the sensitivity of cells to ferroptosis via p62-Keap1-NRF2 signalling pathway, leading to chemoresistance and tumour progression." (PMID 38228715, 2024). "Western blot results in tumor tissues showed that erastin can increase the expression of SOCS2, but inhibit SLC7A11 and GPX4 expression, which can be further promoted by POU6F1 or lncRNA-CASC2 overexpression." (PMID 38267746, 2024). "The IHC staining of xenografts tumor tissues showed that the protein levels of NRF2 and GPX4 were significantly reduced in C5aR-KO mice." (PMID 39483473, 2024). "Establishment of the relationship between GPX4/A2AR and IL-7Rα–mediated signaling in naive and tumor antigen–experienced T cells warrants further investigation." (PMID 38441967, 2024). "To further investigate the occurrence of ferroptosis, we conducted immunohistochemical staining for GPX4 and SLC7A11 in the subcutaneous tumor tissues of the nude mice." (PMID 39771583, 2024). "The tumor sample analysis showed that SLC7A11 and GPX4 mRNA expression were notably decreased in G−LPQDEA/shSLC7A11-treated tumors compared to the control group." (PMID 38399303, 2024). "Compared with the pcDNA3.1-NC group, increased TRAIL reduced the expression of FTH1, GPX4, and SLC7A11 in tumor tissues (P < 0.01)." (PMID 38383815, 2024). "Blocking the process of converting phospholipid hydroperoxide (PLOOH) by the ferroptosis regulator GPX4 leads to the accumulation of PLOOH and produces a tumor suppressor effect." (PMID 38200525, 2024). "Accordingly, therapeutic strategies based on the key targets of ferroptosis, such as GPX4, ferroptosis suppressor protein 1 (FSP1) and GCH1, are capable of reversing cancer drug resistance and interrupting tumour progression." (PMID 39163517, 2024). "In contrast, overexpression of GPX4 or depletion of CD36 can save the effective death of cytotoxic CD8+ T cells and enhance their anti-tumor ability." (PMID 39359721, 2024). "Subcutaneous tumor models were established, in which the expressions of Ki-67, SOCS2, and GPX4 were detected by immunohistochemistry." (PMID 38267746, 2024). "However, despite the fact that GSH oxidase-like enzymes can disrupt the glutathione peroxidase 4 (GPX4)-catalyzed lipid peroxidation repair system and promote the vulnerability of cells towards ferroptosis, they are generally incapable of directly inducing strong ferroptosis effects in tumor cells." (PMID 38462597, 2024). "Through phosphorylation of the downstream SREBP1-SCD1, mTOR1 facilitates the synthesis of GPX4 and GSH, thereby enhancing the resistance of tumor cells to ferroptosis." (PMID 39399463, 2024). "Second, the released SFN from SFN/BQR1@MSPION3 in the tumor microenvironment (TME) can inhibit the system Xc−, and decrease intracellular cystine, GSH and GSH peroxidase 4 (GPX4) levels, thereby enhancing LPO accumulation." (PMID 38658948, 2024). "As given that knockdown FTO enhances the anti-tumor effects of Erastin and RSL3, which targets SLC7A11 and GPX4, respectively." (PMID 38600610, 2024).
tumor (continued). "Inhibitors of GPX4 including RSL3 and FIN56 can induce its degradation within tumor cells, leading to ferroptotic initiation." (PMID 39573995, 2024). "We next examined the effect, in tumor cells, of NCF-1 expression on the intracellular levels of regulators (glutathione synthetase (GSS) and glutathione peroxidase 4 (GPX4)) and a mediator (glutathione (GSH)) of ROS production." (PMID 39666242, 2024). "Sanguinarine (SAG) could reduce the protein stability of GPX4 via E3 ligase STUB1-induced ubiquitination and degradation of GPX4, then increase ROS, MDA, and Fe2+ levels, and finally cause the ferroptosis of NSCLCs and suppress tumor growth and metastasis in vivo." (PMID 38247539, 2024). "Similar with the data from subcutaneous tumor model, IHC and western blotting analyses revealed significantly lower expression levels of Ki67, SLC7A11, and GPX4 in the SFN treatment group." (PMID 39657365, 2024). "A HepG2 cell–transplanted tumor model was established in nude mice, and CK inhibited the growth of transplanted tumors in nude mice, p-FOXO1 was decreased in tumor tissues, and SLC7A11 and GPX4 expressions were also down-regulated after CK treatment." (PMID 38664638, 2024). "IrS NPs deplete GSH in tumors and inhibit GPX4 expression, which generates the LPO and induces ferroptosis in tumor cells." (PMID 37894410, 2023). "In combination with dabrafenib and trametinib, ferrostatin-1 enhances tumor growth of xenografted mice bearing A375GPX4−/− cells, while ferrostatin-1 withdrawal results in inhibiting the growth of GPX4−/− tumors." (PMID 37795022, 2023). "ML162 is a specific inhibitor of GPX4, and the nanomedicine C-ML162 constructed by combining it with Ce6 can accumulate at the tumor site and have strong therapeutic effects." (PMID 37894410, 2023). "The androgen receptor promotes GPX4 overexpression in the luminal androgen receptor subtype of TNBC, which assists tumor cells in escaping ferroptosis." (PMID 37064872, 2023). "In a xenograft mouse model using NB4 cells, compound 90 (10 mg/kg, ip) efficiently decreased GPX4 and elevated COX‐2 expression in the tumor." (PMID 36658724, 2023). "Before and after the treatment of QLD, we measured several ferroptosis-related biomarkers (SLC7A11, SLC3A2, GPX4, and FSP1) in tumor tissues from the patients with CRPC." (PMID 37576395, 2023). "We also evaluated KI‐67 and GPX4 protein expression levels in tumors by IHC, revealing that VU0240551 efficiently prevented tumor growth and induced tumor ferroptosis." (PMID 36645171, 2023). "Compound 91 markedly enhanced their sensitivity to the GPX4 inhibitor 23, further increased lipid peroxidation by interfering with NRF2 signaling, and decreased tumor growth in a mouse xenograft model." (PMID 36658724, 2023). "Recent research has shown that curcumin, as well as Andrographis, can inhibit the negative regulators of ferroptosis, namely, GPX4 and FSP1, in colorectal cancer cells, leading to the activation of the ferroptosis cascade and subsequent anti-tumor effects." (PMID 37371948, 2023). "Higher expression of GPX4, lower expression of NOX1 and FACL4 indicated larger primary tumor size (p = 0.001)." (PMID 35855531, 2023). "Immunoblot showed that in tumor grinding cells of HGC-27-Vector/HGC-27-CST1/HGC-27-GPX4#sh, CST1 overexpression increased the expression of the GPX4." (PMID 36369321, 2023). "Since lipid ROS production is suppressed by GPX4, we observed, as expected, that RSL3 treatment significantly increased the lipid ROS level in the tumor cells." (PMID 36672246, 2023). "The SLC7A11 inhibitors sulfasalazine and erastin, and the GPX4 inhibitor RSL3, suppress tumor growth in vitro and in vivo." (PMID 37381723, 2023). "In this study, inhibiting AKT phosphorylation clearly inhibited tumor growth in vivo and in vitro, and the expression levels of FTO and GPX4 were downregulated." (PMID 38102129, 2023).